RN7SKP234 (RN7SK pseudogene 234)
Gene: Miscellaneous RNA gene on chromosome 3 (174,057,641 to 174,057,864, forward strand). Ensembl gene ENSG00000252982.
Homologues: Orthologues: guinea pig 7SK (59% identical), mouse Gm56293 (46% identical). Paralogues in human: RN7SKP224 (67% identical), RN7SKP262 (66% identical), RN7SKP78 (66% identical), RN7SKP133 (65% identical), RN7SKP192 (65% identical), RN7SKP6 (65% identical), RN7SKP25 (65% identical), RN7SKP59 (64% identical), RN7SKP235 (64% identical), RN7SKP282 (64% identical), RN7SKP38 (64% identical), RN7SKP69 (64% identical), and 284 more.